RN7SL123P (RNA, 7SL, cytoplasmic 123, pseudogene)
Gene: Miscellaneous RNA gene on chromosome 9 (6,661,651 to 6,661,942, forward strand). Ensembl gene ENSG00000266863.
Homologues: Orthologues: chimpanzee Metazoa_SRP (96% identical). Paralogues in human: RN7SL154P (82% identical), RN7SL134P (81% identical), Metazoa_SRP (81% identical), RN7SL474P (80% identical), RN7SL811P (80% identical), Metazoa_SRP (79% identical), RN7SL784P (79% identical), RN7SL96P (79% identical), Metazoa_SRP (78% identical), RN7SL339P (78% identical), RN7SL488P (78% identical), RN7SL774P (78% identical), and 712 more.